SPP1 (secreted phosphoprotein 1)
Diseases named in the same sentence as SPP1 in open-access papers (continued):
Sharing a sentence is not in itself a finding about the gene and the disease.
intrahepatic cholangiocarcinoma (11 papers, 2011 to 2025). A carcinoma that arises from the intrahepatic bile duct epithelium in any site of the intrahepatic biliary tree. "Similar Spp1-driven intercellular interactions have also been observed between my/mesCAFs and iCAFs in murine models of intrahepatic cholangiocarcinoma." (PMID 40678531, 2025). "In our data, SPP1 was strongly expressed in intrahepatic cholangiocarcinoma and S100P had predominant expression in distal bile duct and gallbladder adenocarcinoma, but there were also many cells without either SPP1 and S100P expression." (PMID 39417106, 2024). "In the context of intrahepatic cholangiocarcinoma (iCCA), there were more SPP1+ macrophages that infiltrated the peripheral small duct type of S100P-SPP1 + iCCA." (PMID 38919629, 2024). "Through scRNA-seq analysis of intrahepatic cholangiocarcinoma, S100P and SPP1 are regarded as two biomarkers for two intrahepatic cholangiocarcinoma molecular subtypes." (PMID 36171879, 2022). "Consistent with our findings, a recent oligonucleotide microarray study reported that SPP1 was the most highly expressed gene in intrahepatic cholangiocarcinoma." (PMID 21333016, 2011). "Indeed, a study on intrahepatic cholangiocarcinoma (ICC) revealed S100P and SPP1 as two potential biomarkers to study this tumour heterogeneity, with SPP1+ TAMs numerosity being particularly high in ICC peripheral small duct type compared to ICC perihilar large duct type." (PMID 40395129, 2025).
pneumonia (11 papers, 2010 to 2025). An acute, acute and chronic, or chronic inflammation focally or diffusely affecting the lung parenchyma, caused by an infection in one or both of the lungs (by bacteria, viruses, fungi, or mycoplasma.). "An abundance of SPP1+ macrophages in the alveolar spaces and high SPP1 plasma levels were unique to severe COVID-19 pneumonia as compared with pneumonias induced by other pathogens." (PMID 34143756, 2021). "In Baladi goats with pneumonia and healthy control group, PCR-DNA sequencing revealed SNPs linked to pneumonia susceptibility and resistance in immunological genes (SLC11A1, CD-14, CCL2, TLR1, TLR7, TLR8, TLR9, defensin, SP110, SPP1, BP1, A2M, ADORA3, CARD15, IRF3, and SCART1)." (PMID 40221769, 2025). "The immune genes’ mRNA levels in goats (SLC11A1, CD-14, CCL2, TLR1, TLR7, TLR8, TLR9, defensin, SP110, SPP1, BP1, A2M, ADORA3, CARD15, IRF3, and SCART1) varied between the healthy and infected goats with pneumonia." (PMID 40711280, 2025). "Through PCR-DNA sequencing in Baladi goats with and without pneumonia, SNPs linked to pneumonia susceptibility and resistance were discovered in the immunological (SLC11A1, CD-14, CCL2, TLR1, TLR7, TLR8, TLR9, defensin, SP110, SPP1, BP1, A2M, ADORA3, CARD15, IRF3, and SCART1) genes." (PMID 40711280, 2025). "The levels of immunological genes (SLC11A1, CD-14, CCL2, TLR1, TLR7, TLR8, TLR9, defensin, SP110, SPP1, BP1, A2M, ADORA3, CARD15, IRF3, and SCART1) vary in goats with and without pneumonia." (PMID 40221769, 2025). "Real-time PCR was conducted to quantify the expression levels of immunological markers (SLC11A1, CD-14, CCL2, TLR1, TLR7, TLR8, TLR9, β defensin, SP110, SPP1, BP1, A2M, ADORA3, CARD15, IRF3, and SCART1) in Baladi goats with and without pneumonia resistance." (PMID 36977224, 2023).
steatosis (11 papers, 2010 to 2025). Increased lipid within the cytoplasm of cells. "Liver tissues had more serious steatosis, hepatocyte ballooning degeneration, and lobular inflammatory infiltration, and the expression of SPP1 and CXCL9 in liver cells was significantly upregulated in NASH patients compared to healthy controls." (PMID 35514751, 2022). "Six progress-related genes (AKR1B10/SPP1/CD24/UBD/FABP4/STMN2) were found remarkably correlated with steatosis, ballooning, inflammation, fibrosis, and NAS in the progress of Normal/NAFL/NASH." (PMID 33574818, 2020). "Surprisingly, expression of Acaca was comparable between WT and Spp1−/− mice, while Srebf1, Fasn and Scd1 where even significantly downregulated in the Spp1−/− genotype, indicating that the increased steatosis observed in Spp1−/− mice cannot be explained by enhanced de novo lipogenesis (dnl)." (PMID 32281248, 2020).
adenoma (10 papers, 2009 to 2025). A neoplasm arising from the epithelium. "Following TGF-β1 exposure, we identified genes with extremes of differential expression by genotype, including reduced Id1 and increased Spp1 gene expression as consistent features in Smad4Δ/Δ murine adenoma organoids." (PMID 40348815, 2025). "The other two genes, DCN and SPP1, were down-regulated in adenoma, AEM and AEC, and up-regulated in advanced carcinoma." (PMID 33322258, 2020). "Immunohistochemical reaction for SPP1 was also similar in adenoma and AEM, in both epithelial cells and in the stroma." (PMID 33322258, 2020). "The aim of this study was to determine whether the expression of selected ECM-related genes (DCN, EPHA4, FN1, SPARC, SPON2, and SPP1) was similar in adenoma and AEM but differed from the expression in AEC and advanced carcinoma." (PMID 33322258, 2020). "We found upregulation of SPP1 in cancer-normal and cancer-adenoma comparisons." (PMID 31211760, 2019). "Because Ereg and Spp1 (among others) are elevated at early (during promotion) and late (during progression) stages, these genes may play a role in the transition from initiated cell through promotion (adenomas) to progression (carcinomas)." (PMID 19925653, 2009). "In the cancer-adenoma comparison, upregulation of DEGs involved in cell invasion/migration (POSTN, SPP1) and downregulation of DEGs involved in Paneth differentiation (DEFA5/6) were observed." (PMID 31211760, 2019). "Some of these genes have already been reported in adenoma compared to carcinoma, such as SPON2, SPP1, and SPARC, which is validation for our own analysis." (PMID 30175151, 2018). "Several interactions only occurred in specific locations, such as signalling pathways of CALCR, RANKL and TWEAK in the submucosa, GDNF, GDF, IL12, CD30 and CD137 signalling pathways in the adenoma, and PD‐L1, GP1BA, RESISTIN and SPP1 signalling pathways in tumour." (PMID 39934971, 2025). "For Spp1, the high overall mRNA expression in adenoma derived organoids was not matched in the caecal derived single cell mRNA in epithelial cells, presumably as expression was confined mainly to the monocyte-macrophage lineage not present in organoid cultures." (PMID 40348815, 2025).
astrocytoma (10 papers, 2016 to 2025). "Our findings substantiate a model for T cell exclusion in IDHmt astrocytoma in which microglia produce SPP1 and IL-1β, thereby enabling crosstalk with CD44 and IL-1R-positive GTCs, a process that is highly reminiscent of glial scarring." (PMID 39880824, 2025). "Overall, the seven TAM populations were observed to be contributing in an increased capacity to pathways such as SPP1, COMPLEMENT, GALECTIN and PTN compared to their counterparts in IDH-mutant astrocytoma." (PMID 38012322, 2023). "qRT-PCR showed stronger expression of SPP1, and TGF-β1, in most astrocytoma samples of both grade II and IV compared to normal brain sample." (PMID 34162919, 2021). "To elucidate if the protein level in blood serum is related with the presence of brain tumours, we investigated the mRNA expression of TIMP-1, ANGPT1, SPP1 (OPN coding gene), IP-10, TGF-β1 and TIMP-1 in astrocytoma samples as well as in healthy human brain tissue." (PMID 34162919, 2021).
emphysema (10 papers, 2014 to 2025). "While plasma OPN levels have been associated with exposure to air pollution, which in turn was linked to worsening emphysema, the mechanistic link between particle exposure triggered SPP1 and COPD development has so far only been drawn for CS." (PMID 39877287, 2025). "Elevated levels of SPP1 in sputum are associated with neutrophilic inflammation and the extent of radiographic emphysema, the most common subtype of COPD, highlighting its correlation with disease severity." (PMID 40559389, 2025). "Mechanistically, Shan and colleagues have elegantly shown in a CS‐induced mouse emphysema model, that by lung phagocytes released SPP1 mediates emphysema development via activating Th17 signaling, as Th17 cells and emphysema development was reduced in OPN deficient mice." (PMID 39877287, 2025). "On the other hand, SPP1 is associated with neutrophilic inflammation and emphysema." (PMID 33626243, 2021). "Ada−/− mice is another model of COPD, and Spp1−/−Ada−/− double knockout mouse leads to reduced histopathologic and biochemical features of pulmonary inflammation and emphysema, primarily by attenuating neutrophil recruitment and SPP1-dependent MMP9 production." (PMID 40559389, 2025). "For example, lung dendritic cells from patients with emphysema exhibit higher SPP1 expression compared to controls." (PMID 40559389, 2025). "To study the expression of SPP1 during COPD development, we analyzed SPP1 messenger RNA (mRNA) levels from either emphysema or COPD patients across four different cohorts." (PMID 39877287, 2025). "Consistently, we found that SPP1 is significantly elevated in lung tissue of either emphysema or COPD patients compared to controls, supporting the clinical relevance of SPP1 induction during COPD development." (PMID 39877287, 2025). "Among these markers, Mmp12 and osteopontin (Spp1) are essential for the development of smoke-induced emphysema in mice whereas MMP-12/SPP-1 levels in sputum were shown to correlate with the extent of emphysema in COPD patients." (PMID 38348034, 2024). "A recent study demonstrated that cigarette smoke-dependent up-regulation of SPP1 expression mediates induction of emphysema in an experimental mouse model." (PMID 25248511, 2014). "In summary, our data suggests a crucial contribution of SPP1+ macrophages to environmental particle pollution‐related emphysema development and thus SPP1+ macrophages may provide a potential preventive target for COPD." (PMID 39877287, 2025). "Noteworthy, carbonaceous particle exposure‐induced Spp1 expression in the animal model positively correlated with emphysema‐like changes, highlighting the contribution of SPP1 to the development of air pollution‐related emphysema." (PMID 39877287, 2025). "Also, the deactivation of PPARγ, a negative regulator of Th17 differentiation and Spp1 expression, leads to lung inflammation and emphysema development." (PMID 39877287, 2025). "In addition, smoking can increase SPP1 expression, and subsequently induce inflammation and emphysema." (PMID 25318463, 2014). "Additionally, Spp1−/− mice were protected from developing emphysema after smoke exposure." (PMID 40559389, 2025). "Interestingly lung Spp1 mRNA levels correlate with emphysema‐like changes, that is, the MCL value (p = 0.0087), indicating the strong association between SPP1 induction caused by CNP exposure and emphysema development." (PMID 39877287, 2025).
esophageal squamous cell carcinoma (10 papers, 2015 to 2025). Esophageal squamous cell carcinoma (ESCC) is a type of esophageal carcinoma (EC) that can affect any part of the esophagus, but is usually located in the upper or middle third. "In the context of esophageal squamous cell carcinoma, high expression of SPP1 was found to facilitate the accumulation of M2-like TAMs, correlating with poor prognosis." (PMID 38806553, 2024). "The single cell RNA sequencing data of myeloid cells integrated from several cancers including esophageal squamous cell carcinoma was analyzed for characterizing the function and cellular interactions of SPP1 + macrophages expressing SIRPα." (PMID 39696410, 2024). "Global single-cell transcriptome analysis using data from clinical trials demonstrated that TAMs highly expressed APOE, APOC1, and SPP1 genes in patients with esophageal squamous cell carcinoma (ESCC) post-neoadjuvant chemotherapy, and this leads to an increase in M2-like macrophages." (PMID 38787372, 2024). "We analyzed two single-cell RNA sequencing (scRNA-seq) datasets (GSE145370 and GSE160269) of esophageal squamous cell carcinoma to identify a novel TREM2-positive TAM subpopulation characterized by upregulation of TREM2, C1QC, C1QB, C1QA, SPP1, and APOE." (PMID 37187751, 2023).
gastric adenocarcinoma (10 papers, 2011 to 2023). "One of the other genes from our RNA-seq data shown to regulate radiation sensitivity was SPP1 in gastric adenocarcinoma." (PMID 36627902, 2022). "This study is the first to indicate that SPP1 can be utilized as a gene target for enhancing radiotherapy sensitivity of gastric adenocarcinoma, triggering the Wnt/β-catenin pathway." (PMID 34367279, 2021).
mesothelioma (10 papers, 2010 to 2025). A usually malignant and aggressive neoplasm of the mesothelium which is often associated with exposure to asbestos. "In individuals with a history of asbestos exposure, a serum SPP1 level above 48.3 ng/mL yields a sensitivity of 77.6% and a specificity of 85.5% for diagnosing mesothelioma, with even higher accuracy observed in patients with stage I disease." (PMID 40559389, 2025). "Finally, RNA sequencing of KPM cells comparative to normal pleural mesothelial cells revealed a distinctive transcriptomic signature that included classic mesothelioma markers (Msln, Spp1, Efemp1, Pdpn, Wt1) as well as new candidate mesothelioma genes." (PMID 34898002, 2022). "Their expression was confirmed in MM cell lines after miR-503 inhibition, while in human mesothelioma tissues we found a reverse expression only for CXCL8, Serpine1, and SPP1 compared to the cells." (PMID 39984959, 2025). "The clinical studies related to SPP1 are limited in disease prediction and diagnosis, such as metastatic breast cancer (NCT04274504) and mesothelioma (NCT02029105)." (PMID 39529085, 2024). "Moreover, SPP1 levels are also elevated in the pleural fluid from mesothelioma patients compared to those with non-mesothelioma etiologies." (PMID 40559389, 2025).
ovarian tumor (10 papers, 2015 to 2025). "In ovarian tumor tissues, SPP1 overexpression was significantly associated with poor survival and indicated higher levels of immune cell infiltration." (PMID 39409192, 2024). "SPP1 was found to be overexpressed in ovarian tumor tissues and high SPP1 expression was correlated with shorter survivals." (PMID 36585688, 2022). "Moreover, sensitivity to cisplatin was also improved in a mouse ovarian tumor model using anti-SPP1 and anti-CD44 antibodies." (PMID 38515213, 2024).
prostate tumor (10 papers, 2007 to 2025). "Elevated expression of SPP1 has been correlated with poor prognosis in prostate tumors and other cancers and it has often been implicated in metastasis to bone and other organs." (PMID 17430594, 2007). "Previous studies have indicated that prostate tumor cells secrete SPP1 protein to attract infiltrating MDSCs." (PMID 39066845, 2024). "SPP1 and CLDN8 were upregulated in prostate tumor tissues, whereas COL4A6, RND3, DPT, EFS, and TGFB1I1 were downregulated." (PMID 37251946, 2023). "In our current study, we identified Spp1, known as osteopontin, as another macrophage-secreted cytokine that promotes prostate tumor progression through upregulation of PIN cell growth without affecting cell death." (PMID 35457063, 2022).
atrial fibrillation (9 papers, 2020 to 2026). A disorder characterized by an electrocardiographic finding of a supraventricular arrhythmia characterized by the replacement of consistent P waves by rapid oscillations or fibrillatory waves that vary in size, shape and timing and are accompanied by an irregular ventricular response. "While we previously reviewed the perils of epicardial fat on atrial failure, a recent single‐cell transcriptomic analysis of human atria has documented the expansion of SPP1+ macrophage as a promoter of atrial fibrillation." (PMID 41562403, 2026). "For example, in a recent study, SPP1+ macrophages were shown to promote atrial fibrillation in the heart through cross‐talk with local immune and stromal cells." (PMID 39639496, 2025). "The stromal cell protein SPP1 is found to be upregulated in the bloodstream of individuals with atrial fibrillation, thereby stabilizing collagen and fostering fibrosis in hypertensive patients." (PMID 39223947, 2024). "A recent study showed that SPP1+ macrophages promoted atrial fibrillation and that the level of SPP1 in macrophages increased during atrial fibrillation." (PMID 38919629, 2024). "Recent investigations unveil a notable expansion of inflammatory monocytes and SPP1+ macrophages in patients with atrial fibrillation." (PMID 39223947, 2024). "Indeed, Spp1−/− or Ccr2−/− mice showed attenuated atrial fibrillation while macrophage OPN was identified as a mediator of TGFβ1-dependent inflammatory and profibrotic activation of atrial fibroblasts, both in the mouse model and in atrial fibrillation biopsies." (PMID 39595580, 2024). "In a mouse model of atrial fibrillation (the HOMER mouse), scRNASeq revealed the expansion of SPP1+CCR2+ monocyte-derived macrophages as a crucial event in rhythm abnormalities." (PMID 39595580, 2024).
Autoimmunity (9 papers, 2013 to 2025). The occurrence of an immune reaction against the organism's own cells or tissues. "The upregulation of Spp1 (a gene encoding for OPN in rodents) has been associated with autoimmunity-induced inflammation." (PMID 39684790, 2024).
brain injury (9 papers, 2014 to 2025). Acute and chronic (see also brain INJURIES, CHRONIC) injuries to the brain, including the cerebral hemispheres, CEREBELLUM, and brain STEM. "Interestingly, plasma SPP1 closely parallels brain‐derived SPP1 and has been recognized as a novel marker for acute brain injuries." (PMID 39939834, 2025).
cognitive decline (9 papers, 2013 to 2026). "A study based on the ROSMAP reported SPP1 expression was associated with faster cognitive decline, greater odds of AD and CAA, and activated microglia and neuroinflammatory disorders." (PMID 40004604, 2025). "Our results about those peptides associated with the SPP1 protein gene and cognitive decline in the ADAS indicated positive significant correlations for VVSSIEQK at the MCI phase represented in CDR, ADAS-11, and ADAS-13." (PMID 36793451, 2023). "On the other hand, neutralizing Spp1 in 5 × FAD mice reduced Aβ plaque deposition, and increased SPP1 expression in MG was associated with faster cognitive decline in AD patients." (PMID 41549460, 2026). "It is interesting that one DAM2-associated marker, SPP1, showed the opposite results to all other DAM2 markers by predicting faster tau accumulation in Braak III–IV, as well as faster cognitive decline in A+T+ individuals." (PMID 37118533, 2022). "Further, greater levels of SPP1 correlated with cognitive decline in these patients." (PMID 36496454, 2022). "With regard to the GDSVVYGLR and QETLPSK peptides, which are related to SPP1, one study showed a positive correlation between SSP1 and cognitive decline in MMSE scores in AD patients." (PMID 36793451, 2023).
cutaneous melanoma (9 papers, 2010 to 2023). A primary melanoma arising from atypical melanocytes in the skin. "In addition, SPP1 and SPP2 mutations mainly occurred in cutaneous melanoma and endometrial cancer." (PMID 31849319, 2019). "SPP1 was significantly downregulated in kidney renal papillary cell carcinoma (KIRP), kidney renal clear cell carcinoma (KIRC), kidney chromophobe (KICH) and Skin Cutaneous Melanoma (SKCM) than in control normal samples in TIMER database." (PMID 36585688, 2022).
endometrial cancer (9 papers, 2019 to 2025). Primary or metastatic malignant neoplasm involving the endometrium (mucous membrane that lines the endometrial cavity). "EC cells regulated the macrophages polarization by secreting SPP1 enriched exosomes, which finally promoted the angiogenesis of endometrial cancer." (PMID 38956502, 2024).